IL6 (interleukin 6)
Diseases named in the same sentence as IL6 in open-access papers (continued):
Sharing a sentence is not in itself a finding about the gene and the disease.
Obesity (continued). "Furthermore, the increase in both blood TNF‐α and IL‐6 due to obesity was suppressed in KO mice." (PMID 37845194, 2023). "Additionally, obesity may result in the increased secretion of pro-inflammatory cytokines, including TNF-α, IL-6 and CRP, causing chronic inflammation, and the impaired quality and development of embryos." (PMID 36742394, 2023). "Obesity is a proinflammatory state, and the adipose tissue propagates inflammation by recruitment of macrophages via chemokines such as monocyte chemoattractant protein-1, and via elaboration of cytokines and chemokines such as leptin, interleukin-6, and tumor necrosis factor α." (PMID 37535415, 2023). "TGFβ may also induce endothelial cells to produce IL-6, which can contribute to obesity." (PMID 37062827, 2023). "Furthermore, obesity leads to low-grade chronic inflammation and in obese individuals, in addition to the synthesis of pro-inflammatory cytokines (such as IL-6 and TNFα), a reduction of anti-inflammatory cytokines (such as adiponectin) is observed in adipose tissue." (PMID 37653524, 2023). "Accumulating evidence suggests that IL-6 may contribute to the maintenance of normal systemic glucose metabolism and that the increased circulating IL-6 concentrations during obesity may actually be an adaptive mechanism to resist obesity-associated glucose intolerance." (PMID 38136564, 2023). "Thus, IL-6 levels after a 3-month follow-up interval may be an ideal clinical serum bioanalysis to detect the actual effect of NSPT in obesity patients." (PMID 37798684, 2023). "However, obesity-related changes in adipocyte secretory profile (including, e.g., excess synthesis of interleukin 6 (IL-6) and tumor necrosis factor-alpha (TNFα)) attract pro-inflammatory M1 macrophages to perpetuate pro-inflammatory cytokine signaling to trigger adipocyte cell death." (PMID 36979669, 2023). "Interestingly, previous studies have reported that higher BMI contributed to an increased deep-periventricular WMHL ratio, which may be due to obesity leading to higher white matter burden through inflammatory processes, as indexed by elevated IL-6." (PMID 37397447, 2023). "Moreover, adiponectin are reduced in obesity which may be reason for increased release of pro-inflammatory cytokines like IL-6." (PMID 37992066, 2023). "Interestingly, these subjects also show a positive correlation between CSF IL-6 concentrations and serum triglyceride levels, as well as the TC/HDL-C ratio, indicating that obesity and altered lipid profiles are associated with increased central inflammation and greater clinical disability in RRMS." (PMID 37693246, 2023). "At the same time, the serum concentration of IL-6 in obesity group was significantly higher than that in control group and overweight group (2.81 ± 0.39pg/ml in the normal body weight group, 3.19 ± 0.87pg/ml in the overweight group, and 4.47 ± 0.41pg/ml in the obesity group)." (PMID 37231396, 2023). "In our prior study, we show that reactive oxygen species (ROS) generation via CoCl2 or IL-6 treatment enhances this TET1 pathway and ROS neutralization via catalase represses this pathway, potentially explaining the inflammatory hallmark of clinical obesity as a risk factor for TNBC." (PMID 37231419, 2023). "Consequently, elevated serum IL-6 levels are potential biomarkers for obesity-related asthma." (PMID 37834850, 2023). "However, the Toll-like receptor-5-deficient (Tlr5 KO) mouse group, also on a high-fat diet, displayed significantly lower serum levels of IL-6 than the other groups, suggesting that obesity increases the expression of proinflammatory factors, thereby aggravating OA progression." (PMID 38052778, 2023). "Furthermore, the chronic inflammation observed in obesity may be sustained through the persistent activation of p38MAPK and NF-κB signaling and the secretion of the pro-inflammatory cytokines IL-6 and TNFα." (PMID 37821967, 2023).
Obesity (continued). "Similarly, IL‐6 is elevated in those with obesity, as well as in patients with psoriasis." (PMID 37275420, 2023). "Notably, visceral adipose tissue is a significant source of IL-6 in relation to obesity." (PMID 37755259, 2023). "On the other hand, increased IL-6 levels, determined by extrinsic factors such as obesity, social stress, smoking, and pollution, may increase the atherosclerotic risk, as it is associated with increased insulin resistance, hypertension, dyslipidemia, and endothelial dysfunction." (PMID 37629496, 2023). "Moreover, obesity may increase osteoclastogenesis and bone resorption through upregulating proinflammatory cytokines, such as IL-6 and TNF-α, which are capable of stimulating osteoclast activity through the RANKL/RANK/OPG pathway." (PMID 37685327, 2023). "Prominent among the elevated obesity-associated circulating adipokines and cytokines are the C-reactive protein (CRP), Semaphorin-3C (Sema3C), Tumor Necrosis Factor-alpha (TNF alpha), Interleukin-6 (IL-6), Monocyte Chemoattractant Protein-1 (MCP1), and Interleukin-8 (IL-8)." (PMID 38068748, 2023). "Moreover, it has been described that TNFα and IL-6, which are secreted by adipocytes, upregulate PD-L1 in hepatoma and B16-F1 cells, which may be at least partially involved in the role of obesity in promoting tumor progression." (PMID 37107188, 2023). "These variability factors are complex and include age, body weight, obesity, baseline status of patients, liver functions, polymorphisms of drug-metabolizing enzymes, drug interactions, and inflammatory factors such as C-reaction protein (CRP), Interleukin-6 (IL-6) and IL-1β." (PMID 37565064, 2023). "However, while it has been shown that certain proinflammatory cytokines such as TNFα and IL-1β induce hepatic IGF-1 resistance, the contribution of IL-6 signaling in obesity-induced inflammation to hepatic insulin and IGF-1 downstream signaling remains controversial." (PMID 35628414, 2022). "This is a unique system to study solely the IL-6 trans-signalling, without the classic signalling activation, during patho-physiological conditions, including, in our case, obesity associated with insulin signalling and glucose metabolism distortion, as well as physical exercise." (PMID 36387898, 2022). "However, obesity appears to have a stronger effect on IL-6 level." (PMID 36017324, 2022). "Thus, IL-6 is a significant marker of sarcopenia obesity in older." (PMID 35250869, 2022). "It is well known that obesity leads to an elevated inflammatory response and that excess adipose tissue increases the secretion of pro-inflammatory cytokines, markers of inflammation, including interleukin 6, interleukin 8, tumor necrosis factor, and C-reactive protein." (PMID 36388204, 2022). "In this study, blood TNF-α and IL-6 levels increased, but it is highly possible that they were secreted from adipose tissue in addition to the damaged kidneys; thus, it is necessary to investigate the role of adipocytes both in inflammation as well as kidney damage during obesity and aging." (PMID 36289909, 2022). "Interestingly, TGF‐β, a cytokine that along with IL‐6 is important for the Th17 development, is more frequently expressed in the leukocytes of children with obesity and has an inverse relationship with IL‐10 in neutrophils of children with obesity." (PMID 35837843, 2022). "Increasing systemic TNF-α and IL-6 in obesity might impair insulin signaling pathway." (PMID 35409099, 2022). "Moreover, adipose tissue is a reservoir of proinflammatory cytokines, mainly IL-6 and TNFα, and obesity may promote expansion of Th17 cells." (PMID 36159785, 2022). "However, OT intervention exerted a preventive effect on obesity possibly by regulating β-oxidation of fatty acid (Ppara and Pgc1a), cholesterol removal (Lxra), lipolysis (Srebf1 and Hsl), and low-grade inflammation (Il-6 and Il-1b)." (PMID 35967777, 2022).
Obesity (continued). "Moreover, infusion of OCN could substantially downregulate inflammatory related genes (e.g., tumor necrosis factor α (TNFα), IL-1β, and IL-6) and transcription factors in a monosodium glutamate-induced mouse model of obesity." (PMID 35625743, 2022). "Since obesity correlates with low grade inflammation and obese adipose tissue can be heavily infiltrated by immune cells, the mRNA levels of specific immune cell markers (Itgam and Il1b) and of tissue chemokines (Il6 and Ccl2) were quantified in pWAT, eWAT and iWAT." (PMID 36138030, 2022). "Therefore, we believe that although there are numerous and intricate mechanisms involved in the regulation of obesity by IL-6, IL-6 could be a potential target for the treatment of obesity." (PMID 36105933, 2022). "Pro-inflammatory cytokines, such as TNF-α and IL-6, could contribute to systemic insulin resistance or metabolic disorder in obesity, while anti-inflammatory cytokines, such as IL-10 and IL-4, could prevent diet-induced obesity and insulin resistance." (PMID 35807812, 2022). "Hence, in obesity, endothelial cells activated by pro-inflammatory cytokine-activated may contribute to the already elevated serum IL-6 level by secreting more IL-6, as part of a positive feedback loop." (PMID 35557517, 2022). "Therefore, pharmacological compounds targeting adipose tissue inflammation or IL-6 signaling might have the potential to combat obesity." (PMID 36276810, 2022). "However, recent studies have demonstrated that the controversial effect of IL-6 signaling on obesity and insulin resistance might be attributed to its originality." (PMID 35715443, 2022). "While many immune cells including AMs, monocytes, T and B cells infiltrate AT in obesity, the highly significant decreases in IL-1β and IL-6 suggest that inhibition of the inflammasome in AT macrophages could play a pivotal role in the reduction of HFWD-induced cytokines." (PMID 34976743, 2022). "In obesity, DPP4 serum concentration was associated with increased macrophage infiltration of vWAT, high serum levels of leptin, and reduced adiponectin levels, as well as increased circulating levels of inflammatory cytokines, particularly IL-6, IL-12, and TNF-α." (PMID 36499312, 2022). "Interplay between hormones and cytokines may also be important as TNFα, which reduces insulin sensitivity and has been shown to be overexpressed in people with obesity, is partially mediated by leptin in addition to IL-2, and IL-6 cytokines that increase T-cell expansion and liver disorders." (PMID 36143948, 2022). "In addition to osteocalcin, it is also conceivable that Interleukin(IL)-6 is conveyed as a cargo within the EVs from obese participants, based on data in the literature showing that IL-6 serum level are elevated in children with obesity and are elevated following acute exercise." (PMID 36613885, 2022). "For example, increased infiltration of classically activated macrophages (M1) into the adipose tissue and increased production of TNFα and IL-6 are hypothesized to interfere with the normal activity of insulin receptors and contribute to the development of insulin resistance in obesity." (PMID 35684160, 2022). "Thus, small molecules targeting inflammation or IL-6 in adipose tissue might be helpful in limiting excessive basal lipolysis and lipid breakdown in adipose tissue in obesity." (PMID 36276810, 2022). "Furthermore, we hypothesize that IL-6 trans-signalling is mainly involved in glucose metabolism regulation in diet-induced obesity and may be affected by physical activity, while classic signalling is linked to a homeostatic regulation." (PMID 36387898, 2022). "IL-6 is produced by adipocytes and therefore its increased concentration might be due to obesity." (PMID 36174086, 2022).
Obesity (continued). "Further functional resolution of cell- and tissue-specific IL-6 signaling pathways will be important in determining why acute and chronic manipulations of IL-6, whether systemically or specifically in the CNS, produce wide-ranging and seemingly paradoxical effects on obesity." (PMID 35474339, 2022). "Inflammation caused by obesity and lack of physical activity has been considered a primary cause of type II diabetes and atherosclerosis, and is associated with increases in pro-inflammatory cytokines IL-6 and TNF-α." (PMID 36292427, 2022). "Curcumin metabolites may suppress the NF-κB in adipose tissue, and regulate the level of TNF-a, IL-6, monocyte chemotactic protein (MCP-1), plasminogen activator inhibitor type-1 (PAI-1), and increasing adiponectin expression to ameliorate the obesity risk factors." (PMID 36263142, 2022). "We recently observed that exercise-induced reductions in visceral and epicardial adipose tissues were completely abolished in the presence of IL-6 receptor blockade in people with obesity, suggesting that IL-6 may play a central role in regulating adipose tissue mass expansion in humans." (PMID 33572989, 2021). "Similarly to TNF-α, IL-6 levels increase with obesity and body fat." (PMID 34356649, 2021). "Obesity is accompanied by chronic inflammation associated with hypoxia and adipocyte dysfunction, which resultsinappearance of pro-inflammatory cytokines such as TNF-alpha, IL-6, MCP-1, IL-1 beta and IL-17A, likely to play a role in lung injury associated with ARDS." (PMID 34960696, 2021). "In conclusion, our work showed effectiveness in treating obesity-associated diabetes as well as protective effect against CVD as shown by the AIP, which might be partly due to the attenuation of inflammatory mediators, TNF-α and IL-6." (PMID 33737713, 2021). "Inflammatory markers that are increased in obesity, such as tumor necrosis factor-α (TNF-α) and interleukin-6 (IL-6), were associated with increased risk of incident ccRCC, but whether these inflammatory pathways play a causal role in the pathogenesis of ccRCC has not been definitively established." (PMID 34564424, 2021). "Available studies, mostly conducted in the second trimester, report elevated CRP with elevated or unchanged hepcidin, sTfR and IL-6, suggesting that an inflammatory profile is present in pregnant women with obesity and thus could be playing a role in ID/IDA of overweight/obese pregnancy." (PMID 34067098, 2021). "Obesity, a key component of metabolic syndrome, causes adipose tissue remodeling and induces increased secretion of pro-inflammatory adipokines, including TNF-α and IL-6, and decreased anti-inflammatory adipokines like adiponectin, which potentially accelerates hepatocarcinogenesis." (PMID 33427937, 2021). "The characteristic profile of soluble factors in obesity and aging, such as decreased adiponectin, elevated levels of C-reactive protein (CRP), leptin, tumor necrosis factor-α (TNF-α), and interleukin 6 (IL-6), could lead to progressive loss of muscle mass and an increase in fat mass." (PMID 34676021, 2021). "Moreover, adipose interlerkin-6 (IL-6) exhibited homologous alterations by obesity and lipolysis." (PMID 34504646, 2021). "HFD-induced obesity is associated with the infiltration of macrophages into the adipose tissue, which accounts for a higher concentration of proinflammatory cytokines such as TNF-α and IL-6 in the adipose tissue, as well as an increase in inducible nitric oxide synthase (iNOS) expression." (PMID 33498671, 2021). "In addition, hypermethylation at IL-6 was found in Korean women with obesity." (PMID 34670603, 2021). "However, the regulation of IL-6 in adipocytes in obesity setting remains to be explored." (PMID 34831450, 2021).
Obesity (continued). "Therefore, in this review, supported with current literature, we proposed the existence of a positive feedback loop between adipocytes and ATM via IL-6 signaling in obesity and WAT lipolysis concerning ATM persistence, in hoping to provide new insights for studies of obesity-related inflammation." (PMID 34504646, 2021). "Moreover, increased plasma IL-6 levels may predict the onset of T2DM, whereas in AT expression of IL-6, mRNA is positively associated with obesity and augmented in IR." (PMID 34203452, 2021). "From a mechanistic perspective, obesity can drive oncogenesis through the decreased secretion of adiponectin and the chronic production of adipokines, insulin, insulin-like growth factor, inflammatory cytokines and tumour necrosis factor including IL-6 and TNFa." (PMID 34014795, 2021). "In addition to provide the evidence for the existence of a pathogenetic IL-6/IDO1 axis in obesity, our data suggested that IL-6 blockade by TCZ may represent a promising therapeutic option for obese patients." (PMID 34394118, 2021). "However, because obesity is characterized by chronic systemic inflammation, it is known to be a condition associated with increased production of pro-inflammatory cytokines, such as CRP (C-reactive protein) and interleukin-6 (IL-6)." (PMID 34835945, 2021). "In addition, it is known that interleukin-6 (IL-6) increases hepassocin expression 27, indicating that elevated hepassocin might also be involved in obesity-induced IR." (PMID 33390768, 2021). "As the primary mechanism for death due to obesity is likely the immune over-reaction, these patients may benefit to a greater extent from immunomodulatory treatments aimed at the complement system or interleukin-6, which are being studied in clinical trials." (PMID 34178545, 2021). "The tumor-killing effector cells (CD8+ T) were suppressed and the immunosuppressor cells (MDSCs/M2) were over-activated to drive their recruitment and suppressive capacity, which could be mediated by obesity-related molecular markers, such as IL-6, CRP, leptin, IL-1β." (PMID 34350120, 2021). "Some studies suggested several shared risk factors, such as aging, obesity, and chronic inflammation, implicated in the plausible mechanisms of the association between HTN and OA, and there are also several reports that the proinflammatory cytokine interleukin-6 has a vital role in HTN and knee OA." (PMID 33708440, 2021). "Therefore, this evidence may support the regulative role of TNF-α on IL-6 and IL-10 concentration levels in adults with overweight or obesity who experimented an alteration of monocyte metabolism after exercise training." (PMID 34948868, 2021). "Moreover, bulk RNA-Seq revealed an enhanced transcriptional response to LPS at T3 relative to T1 in the lean subjects relative to those with obesity marked by higher expression of pro-inflammatory molecules (IL6, IL1B, TNF) and induction of transcription factors (RELA, IRF1, STAT3)." (PMID 34195568, 2021). "Although high IL-6 in COVID-19 infection has a prominent role in inflammation linked mortality, recent studies showed that colchicine treatment decreased the concentrations of multiple inflammatory molecules, including IL-6, CRP, and resistin in patient with obesity." (PMID 34220807, 2021). "IL6, IL8, IL1B, CXCR4, and FASN showed significantly higher levels, and since FASN polymorphisms have been associated with elevated BMIs, they suggested FASN maybe a genetic biomarker link between obesity and poor PCa outcome." (PMID 33599076, 2021). "SNP also alleviated HFD induced obesity and gut dysfunction in mice, as indicated by the decreasing of intestinal permeability, the increasing expression of ZO-1 and occludin, the decreasing levels of pro-inflammatory cytokine IL-6, and the repairing of gut microbiota dysbiosis." (PMID 34600475, 2021).